MTOR (mechanistic target of rapamycin kinase)
Diseases named in the same sentence as MTOR in open-access papers (continued):
Sharing a sentence is not in itself a finding about the gene and the disease.
multiple myeloma (continued). "We investigated the mechanism by which gene silencing of the mTOR inhibitor, DEPTOR, induces cytoreductive effects on multiple myeloma (MM) cells." (PMID 25568666, 2014). "In summary, our results demonstrate the synergistic effect of decursin and doxorubicin on the induction of apoptosis via the inhibition of mTOR and/or STAT3 signaling pathway in multiple myeloma cells." (PMID 23818927, 2013). "Overall, the combination treatment of decursin and doxorubicin can enhance apoptotic activity via mTOR and/or STAT3 signaling pathway in multiple myeloma cells." (PMID 23818927, 2013). "Given the importance of IGF-1 in myeloma biology, we specifically examined the effect of MK-2206 on inhibiting PI3K/Akt/mTOR pathway in the presence of IGF." (PMID 23185517, 2012). "The analysis revealed that our models identified probes associated with genes involved in pathways closely related to multiple myeloma, such as PI3K-Akt, MAPK, Wnt signaling, BRAF and RAF1 fusion signaling, and mTOR pathways." (PMID 39858113, 2025). "The major mTOR inhibitors, everolimus and temsirolimus, have fared poorly as single agents in MM trials, while the few myeloma-based trials that have included mTOR blockers in various combinations heretofore have not produced published results." (PMID 36768967, 2023). "Of interest, using a low-dose of mTOR-inhibitor, we observed that cell viability was partially rescued from the effects of EPZ015938, indicating a role for mTOR-related pathways in the anti-myeloma activity of EPZ015938." (PMID 35757005, 2022). "MTOR phosphorylation at Ser2481 (which is a marker of mTORC2 activation) was downregulated, leading to downstream repression of AKT phosphorylation at Ser473 and ultimately, to the inhibition of the myeloma cell growths." (PMID 29554968, 2018). "We described 2 signal proteins (p-mTOR and p-ERK1/2) that may play a role in PX12 + BTZ -induced mitophagy and anti-myeloma effects in MM cells." (PMID 29482577, 2018). "Interestingly, we found that HLSC-EVs directly modulated CSC intracellular pathways (Akt, mTOR and Creb), in analogy with the reported effect of MSC-EVs on the direct modulation of protein FAK phosphorylation in myeloma cells." (PMID 30546834, 2018). "In addition, the combined treatment downregulated the phosphorylation of mTOR and its downstream S6K1 and activated the phosphorylation of ERK in three multiple myeloma cells." (PMID 23818927, 2013). "In addition, 3NPs activated several myeloma-related signaling, including JNK1/2/3, ERK1/2 and mTOR." (PMID 36289430, 2022). "Thus, our data demonstrate that mTOR and ERK1/2 phosphorylation could play a role in the effects mediated by BTZ+PX12 treatment in bortezomib-resistant myeloma cells." (PMID 29482577, 2018). "Due to the mTOR pivotal role in the survival of tumor cells, we evaluated its activation in endothelial cells (ECs) from 20 patients with monoclonal gammopathy of undetermined significance (MGUS) and 47 patients with multiple myeloma (MM), and its involvement in angiogenesis." (PMID 29755672, 2018). "We further show that the inhibitory effect on mTOR activity in myeloma cells is partly through the expression of REDD1, a well-established regulator of mTOR activity, which may prove useful in predicting and monitoring responses in patients with MM receiving selinexor and DEX." (PMID 29876006, 2018). "Even more important, p38 inhibitors - which are in clinical trial for diseases such as rheumatoid arthritis, chronic obstructive pulmonary disease, and multiple myeloma - are likely less toxic than PI3K, AKT, and mTOR inhibitors and could therefore be preferred for combination therapies." (PMID 27270648, 2016). "However, the role of PI3K/Akt/mTOR signaling in the maintenance of myeloma CSCs has not been clarified." (PMID 25915427, 2015).
multiple myeloma (continued). "However, therapeutic attempts to interfere with the mTOR/PI3K/AKT pathway using mTORC1 inhibitors (e.g., rapalogs) demonstrated low efficacy against myeloma because of induction of negative feedback circuits increasing mTORC2 activity." (PMID 36172163, 2022).
sarcoma (136 papers, 2010 to 2026). A usually aggressive malignant neoplasm of the soft tissue or bone. "Despite their genetic complexity, these sarcomas share genomic alterations causing PI3K/Akt/mTOR and MAPK pathway activation, and both pathways control translation mediated by the RNA helicase eIF4A." (PMID 41945393, 2026). "Due to the presence of their specific oncogenic driver mutation, these sarcomas are particularly sensitive to mTOR inhibitors." (PMID 36845725, 2023). "While this data serves to bolster previous findings of the unique nature of the EWSR1-NFATc2 fusion, this study also associates EWSR1-NFATc2 fusion positive sarcomas with activation of the mTOR pathway." (PMID 34021224, 2021). "Dysregulation of mTOR-associated signaling pathways has been observed in several malignancies, including sarcomas." (PMID 21837674, 2012). "Since these proapoptotic effects were in contrast to recent data for the dual PI3K/mTOR inhibitor NVP-BEZ23 in sarcoma cells, we investigated the underlying mechanism in more detail." (PMID 23300809, 2012). "The upregulation of growth factors or mutations in tyrosine kinase receptors that belongs to the mTOR network have been reported to be involved in the development of various sarcomas." (PMID 22701332, 2012). "Work by us and others have highlighted the importance of the mTOR pathway and the therapeutic benefit associated with mTOR inhibition in several cancers including pediatric sarcomas." (PMID 20543980, 2010). "We report on two cases of patients with TSC-mutated sarcomas who experienced significant responses to the combination of gemcitabine and sirolimus, after progression on prior gemcitabine-based chemotherapy and single agent mTOR inhibition with nab-sirolimus." (PMID 36845725, 2023). "While this finding is not suggestive of exquisite stabilization of EWSR1-NFATc2 fusion positive sarcomas to mTOR combination therapy, when linked with the other presented evidence a case could be made for mTOR as a potential therapeutic target in this disease." (PMID 34021224, 2021). "Additionally, Akt signaling has been linked to resistance to IGF1 receptor (IGF1R) and mTOR (mammalian target of rapamycin) inhibitors in sarcoma, further demonstrating the role of Akt in tumor survival." (PMID 26402468, 2015). "Other models have suggested that sarcomas associated with PTEN loss or inactivation may be particularly susceptible to the therapeutic effects of mTOR inhibitors." (PMID 22665999, 2012). "BEZ235 was studied because PI3K/mTOR signaling plays a critical role in sarcoma progression, and BEZ235’s inhibitory effects on cancer cell growth are independent of EGFR status." (PMID 40427168, 2025). "We also observed the enrichment of the E2F transcription factor (NES=2.308), MYC target (NES=2.017), and mTOR signaling (NES=1.906) in SARC sarcoma (all P < 0.05)." (PMID 40612679, 2025). "In a mouse sarcoma model, reduced mechanistic target of rapamycin (mTOR) activity, glycolysis level, and IFN-γ production in T cells are attributed to tumor metabolism and are reversed by immune checkpoint blockade." (PMID 41584838, 2025). "Further, clinical trials involving PI3K/AKT/mTOR or HDAC inhibitors in combination with chemotherapeutics are limited with minimal response in sarcomas." (PMID 38927890, 2024). "The PI3K/AKT/mTOR pathway is aberrantly activated in many types of cancers, including sarcomas, and this pathway plays a pivotal role in the development of leiomyosarcomas." (PMID 38758230, 2024). "Trabectedin plus mTOR inhibitors are active in preclinical models of sarcoma, downregulating HMGA1 expression levels and stabilizing tumor growth." (PMID 38758230, 2024). "The combination of mTOR inhibitor with trabectedin was shown to be active in preclinical models of sarcoma, supporting the rationale for future clinical trials in STS." (PMID 38758230, 2024).
sarcoma (continued). "The evidence documents TMG-capped mRNAs are hallmarks of the investigated neoplasms and synergy between TGS1 specialized translation and canonical translation is involved in sarcoma recovery from mTOR inhibition." (PMID 37386121, 2023). "TGS1 failure prevented the anchorage-independent growth of osteo- and hemangio-sarcomas and curtailed sarcoma recovery from mTOR inhibition." (PMID 37386121, 2023). "MC seems also an interesting concept to test the effectiveness of biological agents, such as bevacizumab or mTOR inhibitors, but too few trials have been conducted in children and adults with sarcomas." (PMID 37568826, 2023). "Mechanistically, restricted glucose consumption by T cells in a mouse sarcoma model led to reduced activity of the mammalian target of rapamycin (mTOR), which in turn led to decreased IFN-γ production and glycolytic capacity." (PMID 37180129, 2023). "As a result, the cumulative downregulation of TGS1 required TMG-cap-downregulation and mTOR inhibition and prevented recovery from mTOR inhibitor of all 3 tested sarcomas." (PMID 37386121, 2023). "We have proved through bioinformatics that the expression of the proto-oncogene mTOR in sarcoma cells is increased, and its high expression leads to a low survival rate of patients." (PMID 34696664, 2022). "Deforolimus decreased mTOR signaling in patients with high-grade sarcomas, as evidenced by a reduction in the amounts of the ribosomal protein S6 which is being phosphorylated in tumor sections." (PMID 36109789, 2022). "We also present a case of a 58-year-old male patient with metastatic EWSR1-NFATc2 fusion positive sarcoma who achieved 47 months of disease stabilization when treated with combination mTOR and VEGF inhibition." (PMID 34021224, 2021). "A phase I/II study (NCT03190174) has investigated the combination of nivolumab (an anti-PD-1 monoclonal antibody) with the mTOR inhibitor nab-rapamycin in different sarcoma types, including ES." (PMID 33652741, 2021). "In comparison to EWSR1-FLI1 and EWSR1-ERG, the secondary genomic landscape of EWSR1-NFATc2 fusion positive sarcomas is significantly different and appears to be driven by genes related to the mTOR pathway." (PMID 34021224, 2021). "EWSR1-NFATc2 fusion positive sarcomas demonstrate a unique secondary genomic profile from other Ewing sarcomas driven by mTOR signaling." (PMID 34021224, 2021). "EWSR1-NFATc2 fusion positive sarcomas were genomically distinct from traditional Ewing sarcoma and demonstrated upregulation of the mTOR pathway." (PMID 34021224, 2021). "SAHA in combination with the mTOR inhibitor ridaforolimus showed synergistic effects in sarcoma cells based on the suppression of Akt phosphorylation by SAHA." (PMID 34959719, 2021). "Another mTOR inhibitor, ridaforolimus, has been tested in a single arm trial recruiting patients with refractory sarcomas." (PMID 33917001, 2021). "PEComa patients, if diagnosed in community-based hospitals, should be referred to sarcoma centers for mTOR inhibitor therapy or clinical trial enrolment." (PMID 34442003, 2021). "A phase II study on the efficacy of mTOR inhibitors (ridaforolimus and sirolimus) at treating sarcomas has also been reported." (PMID 33114161, 2020). "On the contrary, in the primary-relapsed sample pairs the recurrent sarcoma cells showed higher mTOR activity with an mTORC2 predominance compared to the primary biopsy material." (PMID 32709151, 2020). "Regulatory failures lead to the activation of the phosphatidylinositol-3-kinase (PI3K)–protein kinase B (Akt)–mammalian target of rapamycin (mTOR) pathway which is common in a variety of sarcomas." (PMID 32709151, 2020). "A research study, in which a designated scrutiny was performed regarding mTOR, showed that nearly 2000 sarcomas exhibited overexpression of mTOR which confirms the critical role of AKT/mTOR pathway in GCTB patients at clinical level." (PMID 32351329, 2020).
sarcoma (continued). "The PI3K/AKT/mTOR pathway seems to play a key role in sarcomas pathogenesis, in line with evidences of dual PI3K/ mTOR inhibition efficacy in uterine leiomyosarcoma patient-derived xenografts." (PMID 31569439, 2019). "Sarcoma therapy will likely involve agents that target PTEN/ALK/MTOR pathway members alone, in combination, or/and with other oncogenic pathways associated with or without standard cytoreductive chemotherapy." (PMID 31416195, 2019). "Blockade of PD-L1 in sarcoma cells inhibits mTOR activity and dampens glycolysis, thereby restoring glucose in tumor microenvironment." (PMID 30925913, 2019). "The response rate (stable disease or better for 2 cycles) in our study was consistent with other studies of relapsed sarcoma combining chemotherapy with mTOR inhibition as were the incidence and severity of adverse events observed." (PMID 30410720, 2018). "Our study was designed to evaluate the ability of mTOR inhibition to overcome the chemoresistance of relapsed sarcomas and in particular the resistance seen in ALDHhigh populations within these tumors." (PMID 30410720, 2018). "For example, blockade of mTOR combined with nivolumab is being tested for antitumour activity in sarcoma (NCT03190174)." (PMID 30545340, 2018). "In the human sarcoma cell line U-2 OS, glutaminolysis has been shown to activate mTOR pathway by modulating GTP binding of RagB." (PMID 28950000, 2017). "Although, mTOR inhibitors were shown to be effective in various sarcoma cell lines, their efficacy in in vivo models is controversial, and they displayed low benefit in clinical trials due to high toxicity." (PMID 29156702, 2017). "We found that IS repressed mTORC1/2 signaling pathways as manifest by the decreased phosphorylation levels of mTOR regulation and substrates proteins in sarcoma cells." (PMID 27056897, 2016). "Upregulation of the mTOR pathway has been demonstrated to be a means of resistance to targeted VEGFRi in metastatic sarcoma." (PMID 27295141, 2016). "Clinical trials to test the safety and efficacy of IGF1R antibodies, sometimes in combination with an mTOR inhibitor, have been performed in sarcoma patients, but only two trials enrolled chondrosarcoma patients." (PMID 27418340, 2016). "In this heavily pre-treated, advanced sarcoma population, the addition of mTOR inhibition to VEGFRi based therapy resulted in a clinical benefit for a subset of patients." (PMID 27295141, 2016). "A recent large randomized phase III trial evaluated the effects of an mTOR inhibitor against metastatic sarcomas." (PMID 26502919, 2015). "The dual PI3K/mTOR inhibitor NVP-BEZ235 displayed more potent activity in pediatric sarcomas, with IC50 values ranging from approximately 6 to 500 nM." (PMID 26402468, 2015). "Other PI3K isoform specific and dual PI3K/mTOR inhibitors have been evaluated pre-clinically in pediatric sarcomas." (PMID 26402468, 2015). "In the last decade, particular attention in sarcoma treatment has been focused on the blockade of mTOR by rapamycin and derivatives, which were reported to inhibit the growth of OS cells lines in vitro and in xenografts." (PMID 26029165, 2015). "Targeted drugs, including mTOR inhibitors, are currently being tested as single agents or in combination with other agents, such as autophagic inhibitors, for the treatment of sarcomas." (PMID 24676456, 2014). "Recent clinical trials have combined anti-IGF1R antibody with mammalian target of rapamycin (mTOR) inhibitors after in vitro and in vivo studies combining the two agents in sarcoma cells demonstrated decreased activation of pAKT." (PMID 25170759, 2014). "A positive phase III trial with the mTOR inhibitor ridaforolimus as maintenance treatment in sarcomas has recently been reported." (PMID 25104960, 2014). "In combination, the mTOR inhibitor, sirolimus, with cyclophosphamide is tolerated by the majority of sarcoma patients with a clinical benefit rate of about 20%." (PMID 24216984, 2013).
sarcoma (continued). "A large prospective study of ridaforolimus, an mTOR inhibitor, in 212 patients with metastatic or unresectable sarcomas showed a clinical benefit rate of 29%, which is greater than the expected rate with standard doxorubicin therapy." (PMID 24216979, 2013). "The participation of mTOR in the genesis of sarcoma is related to the primordial role of the IGF system in these tumors." (PMID 22665999, 2012). "The sarcoma cells were treated with either the dual PI3K/mTOR inhibitor BEZ235 or the PI3K inhibitor BKM120 for 18 hours prior to harvest." (PMID 22619567, 2012). "p-S6 ribosomal protein (Ser235/236) has also recently been recognized as a marker to predict therapeutic effect of an mTOR inhibitor in sarcoma." (PMID 23077520, 2012). "A very rare type of mesenchymal malignant tumor named Perivascular Epithelioid Cell Tumor (PEComa) has been specially related to the mTOR pathway." (PMID 22701332, 2012). "Intrinsic activation of the mTOR pathway in sarcomas is the result of abnormal signaling of these pathways." (PMID 22665999, 2012). "Patients with a high expression of phosphorylated S6 responded better to the mTOR inhibitors, suggesting that this is a promising predictive sarcoma marker for targeted mTOR inhibitor therapy." (PMID 22709827, 2012). "The PI3K/Akt/mTOR signaling pathway represents a promising target for therapeutic intervention, since it is abnormally activated in many different human sarcoma types." (PMID 23300809, 2012). "The evidence from both preclinical and clinical studies supports further study of mTOR-targeting rapalogs in the treatment of various subtypes of sarcoma." (PMID 21837674, 2012). "Alterations of the mTOR signaling pathway are common in malignancies, including several types of sarcoma." (PMID 21837674, 2012). "Due to the many functions that mTOR regulates, its abnormal activity leads to a number of malignancies including sarcomas." (PMID 22701332, 2012). "Several mTOR inhibitors currently are under investigation for possible therapeutic use in the treatment of cancer, including sarcomas." (PMID 21837674, 2012). "The efficacy of mTOR inhibitors has also been explored in patients with a heterogeneous mix of other metastatic sarcomas, in each case with only a modest response rate." (PMID 22943457, 2012). "We report that the dual PI3K/mTOR inhibitor PI103 enhances the efficacy of DOX in several sarcoma cell lines and interacts with DOX in the induction of apoptosis." (PMID 23300809, 2012). "The largest experience in sarcomas has been provided with the study of mTOR inhibitors, particularly with compounds similar to rapamycin such as ridaforolimus, everolimus, and temsirolimus." (PMID 21437217, 2011). "The development of mTOR inhibitors as agents for sarcoma patients requires optimization of dose and regimen, defining informative biomarkers of effective exposure and activity, and rationale for their use in combination with existing or other novel drugs." (PMID 20543980, 2010). "Several oncogenic pathway inhibitors are currently undergoing clinical trial evaluation in sarcoma including drugs targeting the PI3K/mTOR (deferolimus and everolimus), Src (dasatinib and AZD0530), and the Ras/Raf pathway (sorafenib)." (PMID 20368975, 2010). "Specifically, hyperinsulinemia directly activates insulin receptors and the IGF-1/2 receptors on tumor cells, thereby stimulating the PI3K/AKT/mTOR and rat sarcoma/mitogen-activated protein kinase (RAS/MAPK) signaling pathways to further promote tumor cell growth and survival." (PMID 41567806, 2025). "Current guidelines recommend mTOR inhibitor therapy as a potential first-line systemic treatment for advanced PEComas, highlighting its prominent role in achieving disease control in this ultra-rare sarcoma." (PMID 40659896, 2025). "Additionally, a third patient initially diagnosed with sarcoma NOS was identified as having PEComa due to TSC2 loss and was recommended treatment with an mTOR inhibitor." (PMID 38228904, 2024).